CD86 (CD86 molecule)
Diseases named in the same sentence as CD86 in open-access papers (continued):
Sharing a sentence is not in itself a finding about the gene and the disease.
esophageal adenocarcinoma (2 papers, 2020 to 2021). A malignant tumor with glandular differentiation arising predominantly from Barrett mucosa in the lower third of the esophagus. "Another in vitro experiment also confirmed that nano curcumin, which has the effect of inhibiting cell proliferation, can significantly up regulate the expression of costimulatory molecule CD86 in esophageal adenocarcinoma DC." (PMID 35201503, 2021). "TCM from oesophageal adenocarcinoma significantly enhanced CD54 (p < 0.001), CD80 (p < 0.001), HLA-DR (p = 0.001), CD86 (p < 0.001) and CD83 (p < 0.001) compared to LPS-induction in background media alone, cM199 (+)." (PMID 32552799, 2020). "In the LPS-stimulated setting, TCM from 2Gy irradiated oesophageal adenocarcinoma biopsies inhibited levels of CD54, compared to 0Gy patient-matched biopsies (p = 0.024), whereas, the levels of CD80, HLA-DR, CD86 and PD-L1 were not differentially altered." (PMID 32552799, 2020).
Ewing sarcoma (2 papers, 2023 to 2025). A small round cell tumor that lacks morphologic, immunohistochemical, and electron microscopic evidence of neuroectodermal differentiation. "In studies on Ewing Sarcoma, the activation of CD99 in macrophages was shown to induce the secretion of characteristic chemokines such as IL1β, IL6, TNFα, and markers CD80 and CD86 by M1 macrophages." (PMID 41000385, 2025).
fibrosarcoma (2 papers, 2016 to 2024). A malignant mesenchymal fibroblastic neoplasm affecting the soft tissue and bone. "The results also revealed that FDX1 was significantly positively correlated with expression of costimulatory molecules CD80 and CD86 in fibrosarcoma." (PMID 38938647, 2024). "In the T241 fibrosarcoma model, increased surface expression of CD86 on cDCs was observed in the tumor draining lymph nodes of mice treated with anti-CD40 mAb alone and in mice treated with anti-CD40 mAb in combination with sunitinib." (PMID 27385210, 2016).
food allergy (2 papers, 2021). Gastrointestinal disturbances, skin eruptions, or shock due to allergic reactions to allergens in food. "CD86 expression is reportedly upregulated in food allergy in mice, and lowering the expression of this molecule in DCs may thus affect allergen specific T-cell activation." (PMID 34444651, 2021).
glaucoma (2 papers, 2021 to 2023). Increased pressure in the eyeball due to obstruction of the outflow of aqueous humor. "Additionally, our results showed that a single microglia may express both CD206 and CD86, which suggests that individual microglia may undergo a switch from one phenotype to another during the process of glaucoma." (PMID 34952606, 2021).
glomerulopathies (2 papers, 2019 to 2025). "Due to the correlation of CD80 and CD86 expression in many glomerulopathies, the B7-1(CD80)-CTLA-4 and B7-2(CD86)-CTLA-4 interactions have been proposed as a molecular target in the treatment of these diseases." (PMID 31177287, 2019). "First, both MCD and MN showed a broadly concordant upregulation of the PD-1/PD-L1, CTLA-4/CD86 and CD200/CD200R axes across all three levels when compared with healthy volunteers, indicating a globally enhanced inhibitory checkpoint tone in primary glomerulopathies." (PMID 41373530, 2025).
Graves ophthalmopathy (2 papers, 2015 to 2025). An autoimmune disorder of the EYE, occurring in patients with Graves disease. "The present study was designed to investigate the expression of mRNA of the immune regulatory molecules FOXP3, CTLA-4/CD28/CD80/CD86, and CD40/CD40L in the orbital tissues from patients who underwent orbital decompression due to Graves' orbitopathy to assess their role in the inflammatory process." (PMID 25653477, 2015).
head and neck cancer (2 papers, 2022 to 2024). A primary or metastatic malignant neoplasm affecting the head and neck. "Another study confirmed that the keratinocyte line expressing MHC II has the characteristics of the absence of CD80 and CD86 in head and neck cancer, which may be a way for tumors to evade immune surveillance." (PMID 36230722, 2022).
heart failure (2 papers, 2024). Inability of the heart to pump blood at an adequate rate to meet tissue metabolic requirements. "Recent research has shown that in patients with heart failure before cardiac resynchronization therapy (CRT), there is a lower frequency of pDC, which increases CD86 expression post-CRT." (PMID 39421157, 2024). "The effect of Dendritic cell Absolute Count, CD62l- CD86+ myeloid Dendritic cell Absolute Count, CD62l- CD86+ myeloid Dendritic cell% Dendritic cell, CD39+ CD8+ T cell% CD8+ T cell, CD3 on Central Memory CD4+ T cell on heart failure was positive." (PMID 38938655, 2024).
Hepatitis (2 papers, 2021 to 2023). Inflammation of the liver. "Meanwhile, the expression level of CD206 was positively correlated with gender and preoperative hepatitis, and patients with high expression of PD-L1 or low expression of CD86 had poor prognosis." (PMID 37306737, 2023). "A significant increase in the number of DCs in infected mouse livers, with higher CD86 expression and IL-4, IL-10 and IL-12 secretion, suggested that DCs were involved in S. japonicum infection-induced hepatitis." (PMID 34692568, 2021). "Higher numbers of B cells were found in the livers of infected WT mice expressing higher levels of CD69 and CD86, suggesting that hepatic B cells could mediate the T cell response in S. japonicum infection-induced hepatitis." (PMID 34692568, 2021).
Hypertension (2 papers, 2023 to 2024). The presence of chronic increased pressure in the systemic arterial system. "Detailed analysis of cell subpopulations revealed a unique microglial subset expressing CD11b/c, CD163, and CD86 exclusively in early hypertension." (PMID 38115109, 2023). "Our results revealed the existence of a distinct group of microglial cells expressing specific surface markers (CD86, CD11b/c, and CD163) only in early hypertension, represented by cluster 3 (C3)." (PMID 38115109, 2023). "At early-stage hypertension, hippocampal microglia exhibited upregulated CD11b/c, P2Y12R, CD200R, and CD86 surface expression." (PMID 38115109, 2023).
leishmaniasis (2 papers, 2014 to 2020). Infectious disease that is transmitted through the bite of hematophagous female phlebotomine sand flies. "In a murine model of leishmaniasis a blockade of CD86 results in inhibition of Th2 cytokine secretion and enhancement of the Th1-type immune response, while a blockade of CD80 exerts the opposite effect." (PMID 24771983, 2014). "Interestingly, they also showed that the early Th1 immune response that confers protection to L. major in C57BL/6 relies on CD86 signaling, suggesting that the role of CD86 in leishmaniasis may be dependent on the genetic background of the mice." (PMID 32784615, 2020).
leprosy (2 papers, 2014 to 2015). Leprosy is a chronic infectious disease affecting primarily the skin and peripheral nervous system. "This cytokine, which has already been shown to inhibit expression of CD86 on ML infected APC, may have contributed to decreased effector T cell expansion and may favor leprosy relapse." (PMID 25992795, 2015). "Given that B7.1 may utilize a compensatory costimulatory pathway, our previous work has shown that, regardless of the clinical form of leprosy, the addition of anti-CD86, but not anti-CD80, in cultured blood leukocytes led to a down regulation of T cell activation and the proliferative response." (PMID 25992795, 2015).
Lipedema (2 papers, 2022 to 2023). Disorder of adipose tissue characterized by symmetric and bilateral enlargement of the lower extremities due to abnormal deposition of subcutaneous fat often in obese women. "When comparing the marker expression profiles of CD11b+CD64+ cells between lipedema patients and the control group, lipedema patients showed higher levels of CD163, Clever-1, HLA-DR and CD86, and a higher proportion of CD206 expressing cells." (PMID 36605202, 2022).
metastasis (2 papers, 2022 to 2024). The spread or migration of cancer cells from one part of the body (where they first appeared) to another. "CD80 and CD86 expression on the cell surface was significantly positive in cases with Breslow thickness less than 2mm, no ulceration on the tumor surface, clinical stage I-II, and no lymph node metastasis in our study." (PMID 37614091, 2024).
metastatic melanoma (2 papers, 2019 to 2023). A melanoma that has spread from its primary site to another anatomic site. "The first checkpoint inhibitor against cytotoxic T lymphocyte protein 4 (CTLA-4, CD152, ipilimumab; Bristol-Myers Squibb; interacts with CD80 (B7.1), alternatively with CD86 (B7.2)) has been approved in March 2011 in the US for the treatment of patients with unresectable or metastatic melanoma." (PMID 37174080, 2023).
nephritis (2 papers, 2020 to 2022). Inflammation of renal tissue. "Similarly, in response to anti-GBM induced nephritis, EMRMs had higher CD86 expression and TNF production than BMRMs at 2 and 24 h after anti-GBM serum injection." (PMID 32385245, 2020).
non-Hodgkin lymphoma (2 papers, 2021 to 2024). Distinct from Hodgkin lymphoma both morphologically and biologically, non-Hodgkin lymphoma (NHL) is characterized by the absence of Reed-Sternberg cells, can occur at any age, and usually presents as a localized or generalized lymphadenopathy associated with fever and weight loss. "CD80 and CD86 are highly expressed in approximately two-thirds of a cohort of 70 malignant B cell samples from patients with non-Hodgkin lymphoma." (PMID 33868277, 2021).
osteomyelitis (2 papers, 2020 to 2024). An acute or chronic inflammation of the bone and its structures due to infection with pyogenic bacteria. "Conversely, reduced frequencies of CD62L-expressing monocytes and CD86+ plasmacytoid DCs linked to lower osteomyelitis risk suggest that restrained antigen presentation capacity in these populations may mitigate inflammation." (PMID 38650858, 2024).
osteoporosis (2 papers, 2019 to 2025). A condition of reduced bone mass, with decreased cortical thickness and a decrease in the number and size of the trabeculae of cancellous bone (but normal chemical composition), resulting in increased fracture incidence. "Moreover, increased CD86 expression in myeloid dendritic cells and higher percentages of CD8+ and CD8^dim T cells among leukocytes were also observed in association with elevated osteoporosis risk." (PMID 41329541, 2025).
Parkinson disease (2 papers, 2014 to 2024). A progressive degenerative disorder of the central nervous system characterized by loss of dopamine producing neurons in the substantia nigra and the presence of Lewy bodies in the substantia nigra and locus coeruleus. "Through the action of their surface molecule CD86, these dendritic cells can promote the activation and differentiation of T cells, thereby affecting the immune response in Parkinson’s Disease." (PMID 38586828, 2024).
peanut allergy (2 papers, 2021 to 2025). "The study conducted by other researchers also reported similar results, showing that CD86 is an important factor in the induction of peanut allergy and the interaction between CD80 expression on DCs and CTLA-4 expression on T cells are both crucial for the induction of tolerance." (PMID 34177885, 2021). "In a peanut allergy model, animals treated with CTLA-4Ig, anti-CD86, or anti-CD80 plus anti-CD86 achieved successful oral tolerance, but those treated with anti-CD80 were compromised." (PMID 39950084, 2025).
pituitary adenomas (2 papers, 2021 to 2023). "There were significantly higher mRNA levels of PD-L2 (p < 0.0001), CD-80 (p = 0.0035), and CD-86 (p = 0.004) in aggressive pituitary adenomas." (PMID 34745002, 2021). "In this study, we have found that the mRNA expression levels of the ligands for immune checkpoint receptors PD-1 and CTLA-4—namely, PD-L1 and PD-L2; CD80 and CD86, respectively— were all significantly higher in pituitary adenomas than in the normal human pituitary." (PMID 34745002, 2021). "Our results demonstrating increased expression of PD-L2, CD80, and CD86 in aggressive pituitary adenoma samples provide a rationale for studying whether immune checkpoint blockade is effective for tumor control." (PMID 34745002, 2021). "Aggressive pituitary adenomas demonstrated an increased expression of PD-L2, CD80, and CD86 in compared to that of normal human pituitary glands." (PMID 34745002, 2021). "Furthermore, the mRNA levels of CD80 and CD86 were significantly higher in the most aggressive subset of PAs compared to non-aggressive pituitary adenomas." (PMID 34745002, 2021). "The significance of increased CD80 and CD86 expression in pituitary adenomas has not been previously reported, but we hypothesize it predicts an increased reliance on CTLA-4 mediated pathway of tumor suppression." (PMID 34745002, 2021).
pulmonary TB (2 papers, 2015 to 2022). "The results showed levels of HLA-DR and CD86 expression reduced in the group of DCs of active pulmonary TB with liposomes compared to the group of TST-negative and TST-positive individuals." (PMID 36544136, 2022). "However, the interaction of DCs from active pulmonary TB patients with liposomes exhibited an increased level of HLA-DR with low expression of CD86 compared to other groups." (PMID 36544136, 2022). "Our results displaying a decrease in HLA-DR+ and CD86+ monocytes and an increase in CD14+CD16+ cells in pulmonary tuberculosis confirm the results of other investigators." (PMID 26339660, 2015).
pulpitis (2 papers, 2020 to 2025). Inflammation of the dental pulp. "To investigate whether ATF3 promotes macrophage migration in pulpitis, we performed IHC analysis of the M1 macrophage marker CD86 and the M2 macrophage marker CD206." (PMID 39801194, 2025). "In addition to investigating the possible regulatory mechanisms of DEGs, we screened key genes as biomarker candidates for the diagnosis of pulpitis, including PTPRC, CD86, CCL2, IL6, TLR8, MMP9, CXCL8 and ICAM1." (PMID 33046027, 2020).
Rb (2 papers, 2016 to 2022). "Immune-related genes such as CD86, CD19, and CD36 were significantly upregulated in advanced Rb while displaying a low degree of expression of CD81 and CD163." (PMID 35626705, 2022). "Retinoblastoma cell could upregulate CD80 and CD86 on DCs, and stimulated allogeneic T cells proliferation." (PMID 27556503, 2016).
renal fibrosis (2 papers, 2022 to 2024). A final common manifestation of a wide variety of chronic kidney diseases characterized by glomerulosclerosis and tubulointerstitial fibrosis. "Our cell-based experiment also revealed that the knockdown of miR-382 upregulated CD86 expression in Raw264.7 cells, thus proposing another explanation for the role of miR-382 in renal fibrosis." (PMID 35585990, 2022). "Given that our CM boosted macrophage phagocytosis and increased the expression of CD206 and CD163 while decreasing the level of HLA-DR and CD86, CM treatment for cisplatin-induced AKI might be beneficial to prevent the progression of renal fibrosis in vivo." (PMID 38247813, 2024).
schistosomiasis (2 papers, 2015 to 2022). An infectious disease caused by parasitic trematodes of the genus Schistosoma that colonize human blood vessels and release eggs that can cause granulomatous reactions leading to acute (swimmer's itch or acute schistosomiasis syndrome) or chronic disease. "C108 has clear splenic cDC1 phenotype, high CD24 and XCR1, and relatively high CD86, and has clearly distinct group-wise effects: enriched after exposure to maternal schistosomiasis, but relatively reduced after exposure to treatment." (PMID 35833137, 2022).
schizophrenia (2 papers, 2022 to 2024). A major psychotic disorder characterized by abnormalities in the perception or expression of reality. "In comparing the high inflammation subgroups directly, CD86 mRNA was significantly lower in schizophrenia than controls (p = 0.048)." (PMID 35844224, 2022). "Therefore, we measured the following pro- and anti- inflammatory macrophage marker mRNAs : CD64, CD206, IL-10, and CD86 (M2b marker) in the dorsolateral prefrontal cortex of people with schizophrenia and unaffected controls." (PMID 35844224, 2022).
Splenomegaly (2 papers, 2009 to 2015). Abnormal increased size of the spleen. "This again is contrary to MHV-68 infections in the absence of CD40, CD40L or CD80/CD86, where splenomegaly and/or viral load during latency amplification were either similar or lower." (PMID 19621080, 2009).
status epilepticus (2 papers, 2014 to 2019). Status epilepticus is defined as a continuous seizure lasting more than 30 min, or two or more seizures without full recovery of consciousness between any of them. "Uptake of labeled S100B by rat spleen CD4+ or CD8+ and CD86+ dendritic cells was exacerbated by pilocarpine-induced status epilepticus which is accompanied by BBBD." (PMID 24988410, 2014).
thyroid cancer (2 papers, 2018 to 2023). "Significant moderate to strong positive correlations were recorded between PD-L1 and PD-L2, PD-L1 and CD80, and PD-L2 and CD86 in thyroid cancer tissues." (PMID 30123257, 2018). "In our findings, the correlation analysis evidenced a moderate significant covariation between CD80 and CD86 mRNA levels in thyroid cancer tissues." (PMID 30123257, 2018). "Moreover, few studies examined the CTLA-4 ligand (CD80 and CD86) gene expression at the protein level in thyroid cancer cell lines and tissues, including PTC and ATC tissues." (PMID 30123257, 2018).
triple-negative breast carcinoma (2 papers, 2021 to 2022). An invasive breast carcinoma which is negative for expression of estrogen receptor (ER), progesterone receptor (PR), and human epidermal growth factor receptor 2 (HER2). "Bevacizumab increased the amount of non-classical M2b subpopulation CD11b+ CD86+ IL-10+ of TAMs in a triple-negative breast cancer (TNBC) model." (PMID 34209679, 2021).
type 2 diabetes (2 papers, 2011 to 2022). "In agreement, the abundance of CD206, a marker for infiltrating macrophages, and CD86, a marker for all macrophages, was increased in skeletal muscle lysates from men with type 2 diabetes after the recovery period." (PMID 36070371, 2022). "Here we report that adults with type 2 diabetes have significantly up-regulated surface expression of CD40 and CD80 with a lag of 2 and 3 days and significantly elevated CD86, HLA-DR, and CD23 expression at a lag of 4 days on circulating monocytes." (PMID 21169129, 2011).
abdominal abscess (1 paper, 2009). An abscess located in the abdominal cavity, i.e., the cavity between the diaphragm above and the pelvis below. "Interestingly, recent studies suggest CD86, not CD80, plays a dominant role in mediating graft vs. host disease and abdominal abscess formation." (PMID 19672303, 2009).
acute pancreatitis (1 paper, 2018). An acute inflammatory process that leads to necrosis of the pancreatic parenchyma. "We observed decreases in lymphocytes, CD19+, B10, CD19+CD24hiCD27hi cells and lower mean fluorescence intensity (MFI) of CD80 and CD86 on B10 or CD19+CD24hiCD27hi cells in patients with AP, especially in those with severe acute pancreatitis (SAP)." (PMID 30546828, 2018).
Adult onset (1 paper, 2022). Onset of disease manifestations in adulthood, defined here as at the age of 16 years or later. "Enhanced apoptosis of CD8+ T cells and increased expression of pro-apoptotic molecules such as Fas, FasL, and caspase-3 have also been reported in adult-onset SLE and JSLE along with defects in costimulatory and activation pathways and increased expression of co-stimulatory (CD40L, CD86) molecules." (PMID 36232733, 2022).
AIDS (1 paper, 2015). A syndrome resulting from the acquired deficiency of cellular immunity caused by the human immunodeficiency virus (HIV). "In addition to CD14, CD33+ macrophages in AIDS patients co-expressed the Fc receptor γ (CD16) and T cell the co-stimulatory molecules CD80 and CD86." (PMID 26475133, 2015).